PHF6 (PHD finger protein 6)
Diseases named in the same sentence as PHF6 in open-access papers (continued):
Sharing a sentence is not in itself a finding about the gene and the disease.
embryonal carcinoma (1 paper, 2019). A non-seminomatous malignant germ cell tumor characterized by the presence of large germ cells with abundant cytoplasm resembling epithelial cells, geographic necrosis, high mitotic activity, and pseudoglandular and pseudopapillary structures formation. "In contrast, embryonal carcinoma cells showed a strong nuclear expression of PHF-6 (arrow)." (PMID 31565104, 2019). "Notably, PHF-6 expression was markedly higher in embryonal carcinomas, than in seminomas in FFPE samples." (PMID 31565104, 2019).
esophageal carcinoma (1 paper, 2025). A primary or metastatic malignant neoplasm involving the esophagus. "Our findings revealed that PHF6 positively correlated with TMB in stomach adenocarcinoma (STAD), prostate adenocarcinoma (PRAD), stomach and esophageal carcinoma (STES), BLCA, and LUAD." (PMID 41515604, 2025).
Hydrocephalus (1 paper, 2024). Hydrocephalus is an active distension of the ventricular system of the brain resulting from inadequate passage of CSF from its point of production within the cerebral ventricles to its point of absorption into the systemic circulation. "We observed an increased incidence of hydrocephalus with enlargement of the skull in Phf6+/– mice, with 11.5% of 205 monitored mice developing symptoms between 23 and 190 days, with the majority of cases occurring before 33 days." (PMID 39405291, 2024). "On the other hand, in males and females with neural-specific mutation of Phf6, we did not observe an increased incidence of hydrocephalus." (PMID 39405291, 2024).
kidney cancer (1 paper, 2025). Primary or metastatic malignant neoplasm involving the kidney. "PHF6 expression was upregulated in most tumor tissues compared with normal tissues, except for kidney cancer and thyroid carcinoma (THCA)." (PMID 41515604, 2025). "Similarly, using data from the TCGA and GTEx databases, PHF6 expression was significantly higher in most cancer types, except for kidney cancer, ovarian serous cystadenocarcinoma (OV), and adrenocortical carcinoma (ACC)." (PMID 41515604, 2025).
lentivirus infection (1 paper, 2023). Virus diseases caused by the Lentivirus genus. "Besides, we utilized the lentivirus infection technology to knock down PHF6 levels." (PMID 36967443, 2023).
liver cancer (1 paper, 2025). An epithelial or non-epithelial malignant neoplasm that arises from the liver. "The colony formation assays revealed that after PHF6 knockout, the number of colonies in liver cancer and PAAD cells was significantly reduced, and the proliferation ability of the cells was markedly impaired." (PMID 41515604, 2025). "Finally, the role of PHF6 was validated in liver cancer and pancreatic cancer cell lines by cell proliferation assays." (PMID 41515604, 2025). "Knockout of PHF6 inhibited the proliferation of liver cancer and pancreatic cancer cells." (PMID 41515604, 2025). "Therefore, we analyzed the expression and potential biological function of PHF6 in pan-cancer and validated its biological function in liver cancer and pancreatic cancer cells." (PMID 41515604, 2025).
lung carcinoma (1 paper, 2025). "Immunohistochemical results obtained from the HPA database indicated that PHF6 protein levels in lung cancer and prostate cancer were higher than that in normal tissues." (PMID 41515604, 2025).
lymphoid leukemia (1 paper, 2024). A malignant lymphocytic neoplasm of B-cell or T-cell lineage involving primarily the bone marrow and the peripheral blood. "PHF6 (Plant homeodomain-like finger protein 6) is an X-chromosome gene mutated in a variety of myeloid and lymphoid leukemias." (PMID 39004675, 2024). "Combination of Phf6 loss with overexpression of activating mutants of Notch1 or Jak3, or overexpression of wildtype Tlx3 has been shown to cause T-ALL acceleration, while transgenic crosses of Phf6 deletion with Idh2 mutation produce mixed myeloid-lymphoid leukemias." (PMID 39004675, 2024).
pancreatic cancer (1 paper, 2025). "Although our findings indicate that PHF6 knockout markedly slows tumor cell proliferation in liver and pancreatic cancer cells, the underlying mechanism requires further investigation." (PMID 41515604, 2025). "CCK8 assay showed that depletion of PHF6 inhibited cell proliferation in both liver and pancreatic cancer cells." (PMID 41515604, 2025). "The knockout of PHF6 in liver and pancreatic cancer cell lines was utilized to investigate the effect of PHF6 on cancer cell proliferation." (PMID 41515604, 2025). "Additionally, the depletion of PHF6 inhibited cell proliferation in both liver and pancreatic cancer cells." (PMID 41515604, 2025).
paraganglioma (1 paper, 2025). A benign or malignant neoplasm arising from paraganglia located along the sympathetic or parasympathetic nerves. "Furthermore, PHF6 was found to be a prognostic disadvantage factor for DSS in LIHC, pheochromocytoma and paraganglioma (PCPG), prostate adenocarcinoma (PRAD), and PAAD." (PMID 41515604, 2025).
seminoma (1 paper, 2019). A radiosensitive malignant germ cell tumor found in the testis (especially undescended), and extragonadal sites (anterior mediastinum and pineal gland). "Our results show a strong nuclear positivity of the PHF-6 protein in normal spermatogenesis and GCNIS, whereas the expression in seminomas was markedly lower." (PMID 31565104, 2019).
T-cell lymphoma (1 paper, 2015). "In another study, Phf6 expression was elevated in murine T-cell lymphoma, supporting observations of high PHF6 expression in human adult B- and T-lymphoid cells." (PMID 26103525, 2015).
uterine corpus endometrial carcinoma (1 paper, 2023). A endometrial carcinoma (disease) that involves the body of uterus. "Uterine corpus endometrial carcinoma patients with PHF6 mutations had a favourable prognosis in terms of OS (p = 0.021) and DFI (p = 0.031) compared with patients without PHF6 mutations." (PMID 36756714, 2023). "Uterine corpus endometrial carcinoma patients were grouped into low‐PHF6 + PHF6 mutation (L + mutation), high‐PHF6 + PHF6 mutation (H + mutation), low‐PHF6 + PHF6 non‐mutation (L + non‐mutation) and high‐PHF6 + PHF6 non‐mutation (H + non‐mutation) for further analysis of overall survival (OS)." (PMID 36756714, 2023). "Interestingly, our recent studies showed that PHF6 mutations frequently occurred in uterine corpus endometrial carcinoma (UCEC) patients, and PHF6 mutation predicted a favourable prognosis for UCEC patients." (PMID 36756714, 2023).
X-linked intellectual disability (1 paper, 2024). An X-linked intellectual deficiency in which not enough information is known, reported or published to indicate whether a gene causes non-syndromic or syndromic presentations. "PHF6/EphR pathway is impaired in the rare X-linked intellectual disability, BFLS." (PMID 38429579, 2024).
tumor (30 papers, 2012 to 2025). "Subsequently, we explored the correlation between PHF6 and cancer heterogeneity, such as tumor mutation burden (TMB) and microsatellite instability (MSI), as well as cancer stemness." (PMID 41515604, 2025). "It is essential to better understand the underlying mechanisms of PHF6 in the tumour immune microenvironment in UCEC." (PMID 36756714, 2023). "In the last 2 decades, studies have shown that PHF6 plays a significant tumor suppressor role in T-cells and its mutation leads to T-ALL development." (PMID 38812997, 2023). "Noticeably, the clinical outcome of these double-mutated cases in this study was very poor, with a median survival more in keeping with that of patients with PHF6-mutated neoplasms than that of SF3B1-mutated neoplasms." (PMID 36671709, 2022). "Knockdown studies of PHF6 suggest a tumor suppressor role for the protein, as PHF6 deficiency in HeLa cell lines resulted in increased UBF protein levels, and increased DNA damage at the rDNA locus." (PMID 34381727, 2021). "The ultimate effect of these mutations is to inhibit PHF6 function or deplete its levels, and as such, provide supporting evidence that this protein serves as a tumor suppressor." (PMID 34381727, 2021). "Collectively, these findings suggest that PHF6 is a tumour suppressor and that these mutations result in a loss of function, consistent with silencing of the PHF6 promoter by DNA methylation in some T-ALL tumours." (PMID 26103525, 2015). "PHF6 gene is an X-linked tumour suppressor involved in the pathogenesis of T-ALL." (PMID 40171462, 2024). "Additional AML screens by other groups found PHF6 mutations in 3% of screened tumours." (PMID 26103525, 2015). "Somatic PHF6 mutations in human tumours were first described for T-ALL patients." (PMID 26103525, 2015). "In this study, we described the distinct expression patterns of PHF6 in tumours and normal tissues by using comprehensive pan‐tissue and pan‐cancer analysis of RNA‐Seq data from TCGA and investigated the association between the expression of PHF6 and immunocyte infiltration in UCEC patients." (PMID 36756714, 2023). "Based on our observations, we reasoned that PHF6 might function as a tumor suppressor, while PHF6 loss or mutations favors T-ALL initiation by lowering the threshold for subsequent oncogenic transformation in hematopoietic progenitors, and postulated the role in promoting T-ALL development." (PMID 34465864, 2022). "Interestingly, PHF6 mutations are associated with tumours expressing the TLX1 and TLX3 oncogenes." (PMID 26103525, 2015). "To further explore the relationship between PHF6 and anti-tumor drug sensitivity, we calculated the IC50 values of LIHC and PAAD samples based on the GDSC database." (PMID 41515604, 2025). "While the expression of PHF6 often indicated an immunosuppressive tumor microenvironment, characterized by increased immune cells associated with tumor suppression, some exceptions were observed." (PMID 41515604, 2025). "PHF6 often collaborates with other molecules through elevated expression to activate oncogenic pathways, regulate epigenetics, and facilitate tumor growth." (PMID 41515604, 2025). "It is reported that in JAK3 mutation or NOTCH1-induced T-ALL, PHF6 deletion can significantly accelerate the development of the disease, indicating that PHF6 plays a tumor-inhibitory role in T-ALL." (PMID 38336746, 2024). "We found that CDK4 and PHF6 were decreased in tumours from mice implanted with PHF6 KD cells compared with controls." (PMID 36756714, 2023). "We found that the expression of PHF6 was significantly higher in tumour samples than in normal samples in 15 cancers." (PMID 36756714, 2023). "Accordingly, we conducted the immunohistochemistry (IHC) assay in the collected samples and confirmed the higher protein levels of PHF6 in tumor versus normal tissue sections." (PMID 36967443, 2023).
tumor (continued). "NOTCH1 expression in T-cell development depends on plant homeodomain finger protein 6 (PHF6), which plays a tumor suppressor role in T-ALL." (PMID 38812997, 2023). "To further investigate the underlying mechanism of PHF6 in tumour cell cycle, we analysed the mRNA expression of CDK1‐7 (cell cyclin‐dependent kinases) in PHF6 KD HEC‐1‐A cells." (PMID 36756714, 2023). "Apparently, enhanced PHF6 expressions in MDA-MB-231 cells significantly promoted in vivo tumor growth in mice, which was further abolished by HIF1α/HIF-2α DKO." (PMID 36967443, 2023). "Knockdown of PHF6 significantly decreased tumour growth rate in vivo, and the weight of PHF6 KD tumours was much lower than that of the controls." (PMID 36756714, 2023). "Plant homeodomain finger protein 6 (PHF6) is a key player in epigenetic regulation, and its alterations lead to various diseases, including tumours." (PMID 36756714, 2023). "Here, we displayed the expression landscape of PHF6 in tumour samples and normal samples of 33 cancers." (PMID 36756714, 2023). "While the results herein support the tumor-suppressive role of PHF6, they are in contrast to the oncogenic role that is attributed to this molecule in different cancer settings." (PMID 38812997, 2023). "Our study and previous studies suggest that PHF6, a double‐edged sword in tumours, can promote tumour progression or act oppositely to prevent tumour occurrence." (PMID 36756714, 2023). "We identified 23 neoplasms that had mutations in both SF3B1 and PHF6, representing 0.4% of all neoplasms assessed." (PMID 36671709, 2022). "The last two decades have elucidated a role for PHF6 in neurodevelopment and hematopoiesis, and revealed it as a potent tumor suppressor with an exclusive tendency for hematologic malignancies." (PMID 34381727, 2021). "In conclusion, our results reveal an important regulatory role for PHF6 during normal hematopoiesis and provide novel clues towards the tumor suppressor role of PHF6 in T-ALL." (PMID 33251223, 2020). "The drug sensitivity analysis indicated that PHF6 was closely related to tumor drug sensitivity, which could offer potential guidance and assistance for the precise treatment of tumors." (PMID 41515604, 2025). "We observed that PHF6 was positively associated with the expression of RNA m1A machinery in most cancers, suggesting that PHF6 might influence tumor progression by modulating RNA m1A." (PMID 41515604, 2025). "We observed that PHF6 was significantly elevated in tumor tissues in most cancer types." (PMID 41515604, 2025). "PHF6 has been shown to have context-specific roles in tumour suppression and thus it is likely PHF6 may also play stage and context-specific roles in brain development." (PMID 39405291, 2024). "The subcutenous xenograft tumor model indicated that PHF6 KD could restrict the in vivo tumor growth, as indicated by tumor volumes." (PMID 36967443, 2023). "It has been reported that Phf6 loss could significantly accelerate T-ALL development driven by co-mutation with JAK3M511I or with aberrant expression of TLX3, suggesting PHF6 as a tumor suppressor in T-ALL." (PMID 37393343, 2023). "Together, these findings indicated that whether PHF6 was a tumor suppressor or a tumor protein may depend on the specific context in which it acted." (PMID 35503998, 2022). "Wright–Giemsa staining revealed the development of a complex hematolymphoid neoplasm characterized by the coexistence of different populations of atypical cells displaying both lymphoid and myeloid differentiation in VC Phf6 + JAK3M511I mice when compared to the controls." (PMID 34465864, 2022). "Beside the tumor cells, lymphocytes also expressed PHF-6 (arrows)." (PMID 31565104, 2019). "Thus, the downstream functions of PHF6 leading to tumour suppression in specific cell or tissue types (e.g., lymphoid and myeloid) are not necessarily limited to proliferative or cell cycle regulatory processes." (PMID 26103525, 2015).
tumor (continued). "Therefore, PHF6 is generally regarded as having a tumor-suppressive function." (PMID 41515604, 2025). "Additionally, CDK4 OE could promote the growth of PHF6 KD HEC‐1‐A cells, suggesting that PHF6 might regulate the tumour growth through CDK4 signalling pathway." (PMID 36756714, 2023). "In UCEC, high expression of PHF6 decreased the infiltration of CD8+ T cells, CD4+ T cells, activated NK cells and M1 macrophages, which prevented tumour formation via immune surveillance, indicating that PHF6 might be a valuable marker for estimating the abundance of immune cells in UCEC." (PMID 36756714, 2023). "Additionally, we analysed the correlations of PHF6 mRNA expression with clinical characteristics in UCECs from TCGA database, including age (n = 541), clinical stage (n = 544), histological grade (n = 544) and tumour status (n = 523)." (PMID 36756714, 2023). "Altogether, this might lead to a downregulation of PHF6-mRNA, which is a known tumor suppressor." (PMID 36158701, 2022). "Despite PHF6 mutations leading to inactivation of the protein, an analysis of PHF6 expression levels in AML regardless of mutation status revealed that PHF6 protein levels are higher in patients with AML than normal controls, a finding seemingly at odds with its role as a tumor suppressor." (PMID 34381727, 2021). "Nevertheless, animal models have revealed that while PHF6 mutations/deletions may be initial events, they are insufficient for tumor initiation without additional driver mutations." (PMID 34381727, 2021). "Recently, PHF-6 has been described to be involved in regulating rRNA synthesis, which may contribute to its role in cell cycle control, maintenance of genomic integrity, and tumor suppression." (PMID 31565104, 2019). "Exosomal miR-214 also inhibits tumor cell proliferation, migration, and metabolic activity by targeting Pyruvate Dehydrogenase Kinase Isoform 2 (PDK2) and PHD Finger Protein 6 (PHF6) in HCC cell cultures." (PMID 41515889, 2025). "We utilized data from the TCGA Pan-Cancer dataset to explore the correlation between PHF6 and tumor characteristics such as TMB, tumor stemness, and RNA methylation." (PMID 41515604, 2025). "Thus, PHF6 may influence tumor stemness, thereby affecting tumor progression." (PMID 41515604, 2025). "This would be due to the differentiation function of PHF6 and RUNX1, and the tumor-suppressive function of PHF6." (PMID 38418452, 2024). "The infiltration level of M2 macrophages, which promoted tumour progression, was higher in UCEC patients with high PHF6 expression than in UCEC patients with low PHF6 expression." (PMID 36756714, 2023). "Then, we detected the protein expression of PHF6 and CDK4 in tumours from mice implanted with PHF6 KD or control HEC‐1‐A cells." (PMID 36756714, 2023). "In contrast with PHF6's role as a tumour suppressor in T‐ALL, decreased PHF6 expression prolonged the overall survival of AML patients." (PMID 36756714, 2023). "Six overlapping AS events regulated by SF3B4 in tumor samples were finally verified, including 1 SE event (ATP2B4) and 5 RI events in 4 genes (SRSF5, PHF6, SNHG12, KIAA1217)." (PMID 33563334, 2021). "Particularly, that PHF6, other member of the PHF gene family, plays a role of tumor suppressor in T-ALL." (PMID 25057852, 2014). "The expression of ALCAM, CN130, DAXX, GAL1, PHF6 and XPA were significantly correlated with tumor grade and stage." (PMID 23819605, 2013). "We conducted Kaplan–Meier analysis in the Meta-validation cohort and observed that patients with high PHF6 had shorter relapse-free survival (RFS) time than those with low PHF6, in line with the notion that PHF6 correlates with tumor recurrence (log-rank test P = 8.3e − 07, N = 2032)." (PMID 36967443, 2023). "Targeting PHF6 was effective to suppress HIF downstream genes and restrict in vivo tumor growth." (PMID 36967443, 2023).
tumor (continued). "Indeed, CRISPR-Cas9-mediated deletion of PHF6 in a murine BCR-ABL1+; p19-/-; mCherry+ B-ALL cell line resulted in delayed tumor formation after injection in immunocompetent mice compared to wild-type B-ALL cells." (PMID 34381727, 2021). "Furthermore, the relationship between PHF6 and tumor stemness was explored, demonstrating positive correlations between PHF6 and DNAss in OV and negative correlations in CHOL and DLBC." (PMID 41515604, 2025). "While PHF6 is thought to play a tumor suppression role in T-ALL, its role in AML may be pro-oncogenic; one study in mouse models found that PHF6 overexpression may contribute to leukomogenesis, and PHF6 deletion may negatively affect AML development." (PMID 39200232, 2024). "Interestingly, miR-128 is also oncogenically expressed in tumours arising from non-neuronal tissue, including T-ALL, where PHF6 was confirmed as a target." (PMID 26103525, 2015).